EGFR (epidermal growth factor receptor)
Diseases named in the same sentence as EGFR in open-access papers (continued):
Sharing a sentence is not in itself a finding about the gene and the disease.
breast carcinoma (continued). "Notch–EGFR crosstalk has been implicated as a paracrine mediator of estrogen to promote ER−/ER low BCSC survival and proliferation within ER+ breast cancer cell lines and patient samples." (PMID 25566499, 2014). "To investigate the role of EGFR on anti-estrogen resistance, we established ectopic human EGFR expression in human MCF7 breast cancer cells." (PMID 24758408, 2014). "The regulatory role of PTPD1 on EGF signalling, and the pathological role of over expressed EGFR during breast carcinogenesis and metastasis, makes breast cancer an interesting model for studying PTPD1 dynamics." (PMID 25062045, 2014). "Pharmacological compounds can induce apoptosis in lung and breast cancer cells by inhibiting the EGFR pathway, and recent work has demonstrated that Mig-6 actively senses EGF deprivation to directly activate proapoptotic c-Abl in murine epithelial cells." (PMID 24670222, 2014). "We have recently shown that in MCF7 breast cancer cells, flotillin-1 depletion results in a paradoxical up-regulation of EGFR expression due to the increased phosphatidyl-inositol 3-kinase (PI3K) signaling (; see Section 3 below)." (PMID 24709906, 2014). "Targeting the function of epidermal growth factor receptor (EGFR) has failed as an effective clinical option for breast cancer." (PMID 25255930, 2014). "Currently, patients with trastuzumab resistant breast cancers are treated with chemotherapy and lapatinib, a dual pharmacological EGFR and ErbB2 inhibitor that targets the intrinsic kinase domains of these two receptors." (PMID 24709902, 2014). "The HER2/neu oncogene, a transmembrane tyrosine kinase receptor belonging to the epidermal growth factorreceptor (EGFR) family, has been shown to be amplified in up to 30% of human breast cancer cell lines (Slamon etal., 1987)." (PMID 26110069, 2014). "For example, it has been shown that inhibiting autophagy in HER2 overexpressing breast cancer cells, sensitised them to EGFR TKIs." (PMID 24946858, 2014). "The result of Pearson correlation coefficient analysis indicated that a strong correlation of EGFR and PI4KIIα expression existed in these breast cancer patients (r = 0.77, P < 0.01)." (PMID 24801752, 2014). "Results showed that PI4KIIα knockdown reduced EGFR protein level, and the expression of PI4KIIα shows a strong correlation with EGFR in human breast cancer tissues (r = 0.77, P < 0.01)." (PMID 24801752, 2014). "Breast cancer patients treated with epidermal growth factor receptor (EGFR) inhibitor, Gefitinib, suffered relapses, which were due to MAPK inhibition that paradoxically lead to PI3K/AKT activation." (PMID 25122124, 2014). "Our animal studies confirmed daily antithetical oscillation of EGFR’s feedback loops, and analyses of clinical specimens uncovered association between high GR, low MAPK activity and favourable prognosis of breast cancer patients." (PMID 25278152, 2014). "Expression of EGFR has been found in up to 80% of triple-negative (HER2/ER/PgR-negative) breast cancers, and targeting EGFR thus has also been viewed as a potential therapeutic strategy for such disease." (PMID 24707474, 2014). "Basal-like breast cancers (BBCs) are enriched for increased EGFR expression and decreased expression of PTEN." (PMID 25361177, 2014). "Epidermal growth factor receptor (EGFR) is a transmembrane glycoprotein that is overexpressed in breast cancers and can be utilized as a biomarker for imaging." (PMID 25988156, 2014). "The rapid and sustained activation of ERK1/2 and its nuclear translocation stimulated by GPR30/EGFR signals mediated the growth arrest effects of G-1 on ER− breast cancer cells." (PMID 25275589, 2014). "This review will discuss the importance of the EGFR/PI3K/PTEN/Akt/mTORC1/GSK-3 pathway primarily in breast cancer but will also include relevant examples from other cancer types." (PMID 25051360, 2014).
breast carcinoma (continued). "Although the EGFR and its ligands are frequently expressed in breast carcinoma, anti-EGFR agents, such as cetuximab, panitumumab, gefitinib and erlotinib, have produced disappointing results in breast cancer." (PMID 25344915, 2014). "Recently, Cdc42 was reported to promote ubiquitination and lysosomal degradation of E-cadherin through the up-regulation of EGFR signalling and subsequent activation of Rac in breast cancer cells." (PMID 25164084, 2014). "We propose that EGFR genotyping should be further evaluated for their prognostic value in prospective studies of breast cancer survival." (PMID 24629097, 2014). "Using the EGF modified micelle, effect of auger electron therapy against EGFR-positive breast cancer cells was performed." (PMID 25379530, 2014). "ECM1 has important roles in both cancer development and trastuzumab resistance in breast cancer through activation of EGFR signaling." (PMID 25499743, 2014). "Reciprocally, EGFR signaling promotes the invasiveness of some breast cancer cells via integrin recycling." (PMID 25606594, 2014). "It is approved in the US for the first-line treatment of EGFR mutation-positive metastatic NSCLC and it is also being developed for the treatment of a number of other ErbB-driven tumours, including breast cancer and HNSCC." (PMID 24973959, 2014). "Patients with EGFR positive tumours, axillary stage I or II disease, or pathological size <3 cm had significantly better breast cancer specific survival." (PMID 24999743, 2014). "Expression of epidermal growth factor receptor (EGFR) serves as a robust marker for the basal-like subtype of breast cancer (BC) and a biomarker for decreased survival times of BC patients." (PMID 25255930, 2014). "Only EGFR showed prognostic significance in terms of breast cancer specific survival, along with stage and pathological size." (PMID 24999743, 2014). "By using CK5 and EGFR, the basal-like breast carcinoma can be identified and the majority of the TNBC patients show EGFR expression; however CK5 shows the statistically significantly correlation with histological grade." (PMID 25400978, 2014). "Instead, five protein markers - ER, PR, HER2, Cytokeratin 5 (CK5) and epidermal growth factor receptor-1 (EGFR) - can serve as surrogates to classify breast cancers into subtypes analogous to those defined by gene profiling." (PMID 25116921, 2014). "More recently, it was demonstrated that depletion of BRK in breast cancer cells impairs the activation of EGFR-regulated signaling molecules." (PMID 24523872, 2014). "According to the preliminary efficacy of AST1306, HER2 positive breast cancer and EGFR mutant NSCLC are the two cancer types recommended to be further studied in the phase II study." (PMID 24612546, 2014). "These two cell lines were treated with GSI (DAPT) and/or anti-HER1/2 (gefitinib or lapatinib) therapies to deduce the role of Notch–EGFR/HER2 crosstalk in HER± DCIS breast cancer." (PMID 25566499, 2014). "It has been reported that cell density can influence the expression of EGFR in breast cancer and in pancreatic cancer cell lines and that surface expression of HER-2 is regulated post-transcriptionally in mammary epithelial cells by the culture cell density." (PMID 24898067, 2014). "The regulatory connection between PI4KIIα and EGFR/p-HER-2 is also present in primary isolated breast cancer cells." (PMID 24801752, 2014). "Both ER-α36 and EGFR are mainly localized on plasma membrane, they have a positive correlation with each other in breast cancer and endometrial cancer." (PMID 24447535, 2014). "Lapatinib, a dual EGFR HER2 inhibitor used in the treatment of HER2-positive breast cancer has a half-life of 24 h whilst the monoclonal HER2 antibody trastuzumab also used in HER2-positive breast cancer has a half-life of over 5 days." (PMID 24639951, 2014).
breast carcinoma (continued). "β1 is also involved in tamoxifen resistance, and fibroblasts, derived from an estrogen-dependent, spontaneous mammary tumor, produce soluble factors inducing tamoxifen resistance in the epithelial cells through activation of EGFR, PI3K/AKT and β1." (PMID 25606594, 2014). "In veterinary medicine, EGFR protein expression has been detected in numerous tumour types, including canine mammary tumours, primary brain tumours, nasal carcinomas, lung carcinomas and osteosarcomas." (PMID 24454858, 2014). "In preclinical studies with cell lines of non small cell lung, pancreatic, colon, and breast cancer combined inhibition of mTOR and EGFR resulted in a potentiation of anti cancer activity and resensitization of cell lines resistant to EGFR inhibitors." (PMID 22367239, 2013). "All of the TNBC cell lines examined expressed a high level of EGFR compared with the luminal breast cancer cell line, MCF7." (PMID 23601074, 2013). "EGFR expression was reported to be an independently worse prognostic factor for breast cancer, whereas Bcl-2 expression is known to be a favorable prognostic factor for breast cancer." (PMID 24245483, 2013). "Given the heterogeneity of breast cancer cells, it is plausible to suggest that the different outcomes of AnxA6 modulation of EGFR in MDA-MB-231 cells and BT-549 cells are cell type specific and presumably dictated by the level of AnxA6 expression." (PMID 24354805, 2013). "Conversely, ablation of FAM83B from EGFR-dependent breast cancer cells inhibits p110α and AKT membrane localization and AKT phosphorylation." (PMID 23676467, 2013). "Subsequently to address the association between EGFR and EXO1 gene expression, we treated EGFR positive breast cancer cell line, MDA-MB-468, with EGFR inhibitor, gefitinib." (PMID 24147022, 2013). "In this respect, we are currently developing 111In–DTPA–EGFt as a potential Auger electron-emitting radiotherapeutic for EGFR-positive breast cancer." (PMID 23935985, 2013). "ShRNA-mediated FAM83B ablation inhibits MAPK signaling and suppresses the growth of tumor-derived breast cancer cells harboring elevated EGFR signaling or mutant RAS." (PMID 23676467, 2013). "EGFR pathway has been a major target in cancer therapy, as aberrant EGFR signaling is a major feature of many human malignancies including breast cancer." (PMID 23555785, 2013). "Our study demonstrates that long-range interactions of cancer-related loci, including EGFR and IGFBP3, are altered in breast cancer cells, and these alterations are frequently associated with epigenetic changes." (PMID 24019942, 2013). "MAPK and PI3K pathways are both downstream targets of EGFR activation, and in relation to its link to breast cancer, over expression of the EGFR in MCF-7 cells directly leads to a cancerous phenotype and one that is estrogen independent." (PMID 23434903, 2013). "In highly aggressive breast cancers, Her2 is constitutively activated, where it shares tyrosine kinase activity as a binding partner with the EGFR." (PMID 23434903, 2013). "The expression rates of HER2 and EGFR in male breast cancer were comparable with recent findings, but other data for IGF1-R and MET in the male breast cancer literature are unavailable." (PMID 23308200, 2013). "We have recently drawn attention to issues with EGFR testing in breast cancer tumor specimens: in 810 patients less than 10% had breast cancers that stained positively." (PMID 23667487, 2013). "Together, our results suggest that GPR30 interference with the EGFR signaling pathway is an initial factor in development of tamoxifen resistance in breast cancer." (PMID 24289103, 2013). "Our data on EGFR inhibition in CRC are in line with a previous study testing HER-2 directed drugs in breast cancer cell lines cultured with the lrECM 3D on-top assay." (PMID 23555746, 2013).
breast carcinoma (continued). "Another similar trial in women with HER2-positive or EGFR-positive DCIS breast cancer testing the effect of a lower dose of lapatinib (1,000 mg/day) is currently ongoing." (PMID 24069582, 2013). "ERα and EGFR expression in human breast cancer tissue are also inversely correlated; ERα seems to repress EGFR in breast cancer cells." (PMID 24289103, 2013). "As GPR30/EGFR crosstalk intensifies under endocrine therapy, breast cancer develops tamoxifen resistance due to growth stimulation induced by EGFR signaling." (PMID 24289103, 2013). "Except for HER2 and EGFR, little is known about expression of growth factor receptors in male breast cancer." (PMID 23308200, 2013). "For example, studies in breast cancer cell lines have reported that EGFR escapes from the degradative pathway to the recycling compartment, and that this contributes to their enhanced malignant phenotype." (PMID 24244711, 2013). "On the other hand, some genes that are described as recurrently amplified in human breast cancers were affected by losses in at least two tumors (e.g. EGFR, IGFR, and CCND1)." (PMID 24098698, 2013). "In this study, we focused on the indole derivative DPDIM’s effect in breast cancer cells highlighting the EGFR pathway." (PMID 23555785, 2013). "To further understand the role of VPS4B dysfunction in breast cancer, we set out to determine the consequences of altered EGFR signaling: changes in protein synthesis and degradation, as well as protein dynamics in VPS4B downregulated breast cancer cells." (PMID 23431444, 2013). "Breast cancer therapies that target cell surface proteins, such as EGFR and ERBB2 are rare examples of successful biologically informed cancer treatments." (PMID 23840623, 2013). "ER-α36 is known to physically interact with the EGFR/Src/Shc complex and mediate estrogen-induced phosphorylation of epidermal growth factor receptor (EGFR) and c-Src in breast cancer cells." (PMID 24137325, 2013). "Since insensitivity of breast cancers to EGFR targeted therapies presents a clinical challenge, it would be worthwhile to determine if gefitinib in combination with HCQ is broadly effective in the gefitinib-insensitive phenotype." (PMID 24146879, 2013). "Further studies are warranted to provide a rationale for the use of AnxA6 expression status as a predictive marker for basal-like breast cancer and to identify patients with this breast cancer subtype who are more likely to respond to EGFR-targeted therapies." (PMID 24354805, 2013). "While several endocrine-resistant breast cancer models are based on inappropriate activity of the EGFR signaling pathway, the present model shows variable activation of the EGFR downstream cascade." (PMID 24289103, 2013). "The Auger electrons emitted by 111In in the nucleus of EGFR-positive breast cancer cells by 111In-DTPA-hEGF were shown to provide potent cytotoxic effects in vitro and tumour growth-inhibition in vivo." (PMID 23935985, 2013). "EREG is a ligand for EGFR and Her4, and was reported to be part of a set of four genes that promote breast cancer intravasation and metastasis to the lung." (PMID 23758962, 2013). "While these networked transcription and DNA repair genes are up-regulated in leiomyoma from older black women, EGFR networked genes were generally down-regulated, different from its growth promoting networks in breast cancer." (PMID 23785396, 2013). "This is in agreement with our recent results demonstrating that GPER-1 cross-talks with EGFR in breast cancer cell lines." (PMID 23849542, 2013). "The association of AnxA6 expression status with the survival of patients with this breast cancer subtype is consistent with the modulation of the stability of activated EGFR in invasive breast cancer cells by AnxA6." (PMID 24354805, 2013). "Experimental studies have found EGFR/HER1 in general to be low in ER+ breast cancer cell lines probably due to downregulation by estrogens." (PMID 23991224, 2013).
breast carcinoma (continued). "All these results reveal that GPR30, through cytomembrane translocation, enhances its interaction with EGFR, thus increasing Erk1/2 activation, leading to breast cancer proliferation during tamoxifen treatment." (PMID 24289103, 2013). "Antibody-based, affibody-based, or EGF-based molecular probes for EGFR imaging of breast cancer have also been under active investigation." (PMID 23533377, 2013). "In breast cancer, EGFR and ErbB2 expression was found to be under control of the Y-box transcription/translation factor YB1 which is phosphorylated by Akt." (PMID 24304721, 2013). "All these point towards the crucial roles of EGFR and its ligands in the biology of the mammary gland and breast cancer." (PMID 24124521, 2013). "Further in support, our recent studies have also described attenuation of EGFR phosphorylation and suppression of tumor promoting signals in breast cancer cells as well as in human embryonic kidney (HEK)-293 cells transfected with SSTR1 or SSTR5." (PMID 24059654, 2013). "Imaging probes targeting other major cellular receptors or biomarkers, such as VEGF and EGFR, are in demand for breast cancer diagnosis and therapy evaluation especially for triple-negative subtype patients." (PMID 23533377, 2013). "In breast cancer cells, STAT5b was identified as a prominently tyrosine-phosphorylated protein and that expression of the Y845F mutant of EGFR has an inhibitory effect on this event." (PMID 23702846, 2013). "Simultaneous inhibition of EGFR and Notch activity has been shown to result in a synthetic lethality in basal-like breast cancer." (PMID 23863842, 2013). "The chosen biological data set contains the effect of a genome-wide library of miRNA mimics on the expression of proteins in the EGFR-driven cell cycle pathway in a breast cancer cell line." (PMID 24039936, 2013). "Over-expression of epidermal growth factor receptor (EGFR) or insulin-like growth factor-1 receptor (IGF-1R) have been shown to closely correlate with radioresistance of breast cancer cells." (PMID 23777562, 2013). "It has been observed that a high percentage of BRCA1- associated hereditary and sporadic breast cancers are triple negative and express a high proportion of basal like cytokeratins (CK5,14,17), as well as P-Cadherin and HER1/EGFR." (PMID 25285241, 2013). "Our results provide evidence to support RF6 CPPP as a novel approach to target triple-negative and EGFR TKI-resistant breast cancer." (PMID 23593472, 2013). "In earlier studies, various kinds of genetic alterations have been identified as prognostic factors such as HER-2 in breast carcinoma and EGFR gene in NSCLC." (PMID 24349071, 2013). "For example, S1P has shown to interact with TGFβ receptors in esophageal cancer cells, EGFR in breast cancer cells, VEGFR in thyroid cells, and of course its own S1P receptors." (PMID 24970177, 2013). "The epidermal growth factor receptor (EGFR) is the only other growth factor receptor for which expression data is available in male breast cancer, suggesting that EGFR is expressed in 12–76% of cases." (PMID 23308200, 2013). "Using HCA, TEM and molecular analysis we demonstrated in this report that gefitinib, an EGFR TKI, stimulates the appearance of autophagy-associated organelles in phenotypically diverse breast cancer cells." (PMID 24146879, 2013). "EGFR/HER1 is known as an estrogen-responsive gene transcriptionally repressed by estrogens in ER+ breast cancer cells." (PMID 23991224, 2013). "Eukaryotic translation initiation factor 4E (eIF4E1) along with EGFR have been identified as proteins expressed in brain metastatic cells originating from breast cancer." (PMID 24244833, 2013). "FGFR amplification has been found in some basal-like breast cancers, a group that also has EGFR amplification." (PMID 23343422, 2013). "There is evidence demonstrating that estrogen triggers epidermal growth factor receptor (EGFR) pathway through GPR30 in breast cancer cells." (PMID 24039841, 2013).